SLC13A3 (solute carrier family 13 member 3)
Description:
High-affinity sodium-dicarboxylate cotransporter that accepts a range of substrates with 4-6 carbon atoms, such as the citric acid cycle intermediates succinate and alpha-ketoglutarate (2-oxoglutarate), as well as other compounds including N-acetyl-L-aspartate. Transports the dicarboxylate into the cell with a probable stoichiometry of 3 Na(+) for 1 divalent dicarboxylate, rendering the process electrogenic. Can transport citrate in a Na(+)-dependent manner, recognizing the divalent form of citrate rather than the trivalent form which is normally found in blood. Imports itaconate in hepatocytes leading to activation of TFEB-dependent lysosomal biogenesis involved in antibacterial innate immune response.
Synonyms: NaC3; NADC3; SDCT2; ARLIAK
Tractability: Small molecule: a structure with a bound ligand is known. Antibody: UniProt places it where antibodies can reach, with high confidence; its Gene Ontology location is reachable by antibodies, with high confidence; UniProt predicts a signal peptide or a membrane-spanning region; the Human Protein Atlas places it where antibodies can reach. PROTAC: a small molecule that binds it is known.
Target class: SLC13 family of sodium-dependent sulphate/carboxylate transporters; Electrochemical transporter; SLC superfamily of solute carriers; Transporter
Gene: Protein-coding gene on chromosome 20 (46,557,823 to 46,684,467, reverse strand). Ensembl gene ENSG00000158296.
Subcellular location: Cell membrane
Subcellular location (Human Protein Atlas): Plasma membrane
Pathways (Reactome):
Transport of small molecules: SLC-mediated transport of organic anions
Gene Ontology:
Molecular function: alpha-ketoglutarate transmembrane transporter activity; dicarboxylic acid transmembrane transporter activity; glutathione transmembrane transporter activity; protein binding; sodium:dicarboxylate symporter activity; succinate transmembrane transporter activity; citrate transmembrane transporter activity; high-affinity sodium:dicarboxylate symporter activity; solute:sodium symporter activity; transmembrane transporter activity
Biological process: dicarboxylic acid transport; glutathione transmembrane transport; succinate transmembrane transport; citrate transport; transmembrane transport; transport across blood-brain barrier; alpha-ketoglutarate transport; sodium ion transmembrane transport
Cellular component: basolateral plasma membrane; extracellular exosome; plasma membrane; membrane
Genetic constraint (gnomAD): Loss-of-function variants: 33 observed, 49.12 expected, observed/expected ratio (o/e) 0.67, 90% interval 0.51 to 0.9. The upper end of that interval is the gene's LOEUF score, 0.9, which puts it in group 3 of 6, group 1 being the genes least tolerant of losing a copy. Missense variants: 632 observed, 703.8 expected, observed/expected ratio (o/e) 0.9, 90% interval 0.84 to 0.96. Synonymous variants: 297 observed, 301.09 expected, observed/expected ratio (o/e) 0.99, 90% interval 0.9 to 1.09.
Homologues: Orthologues: chimpanzee SLC13A3 (99% identical), macaque SLC13A3 (98% identical), rabbit SLC13A3 (90% identical), guinea pig SLC13A3 (88% identical), mouse Slc13a3 (88% identical), rat Slc13a3 (88% identical), pig SLC13A3 (83% identical), tropical clawed frog slc13a3 (73% identical), dog SLC13A3 (66% identical), zebrafish slc13a3 (65% identical), Caenorhabditis elegans nac-1 (35% identical), Caenorhabditis elegans nac-3 (34% identical), and 6 more. Paralogues in human: SLC13A5 (45% identical), SLC13A2 (43% identical), SLC13A1 (40% identical), SLC13A4 (37% identical), OCA2 (19% identical).
Diseases named in the same sentence as SLC13A3 in open-access papers:
SLC13A3 is named in the same sentence as 26 diseases in open-access papers, as found by Europe PMC text mining. Sharing a sentence is not in itself a finding about the gene and the disease. The quoted sentences say what the papers report.
Canavan disease (3 papers, 2013 to 2024). A neurodegenerative disorder; its spectrum varies between severe forms with leukodystrophy, macrocephaly and severe developmental delay, and a very rare mild/juvenile form characterized by mild developmental delay. "Astroglial conditional Slc13a3 deletion in aspartoacylase‐deficient Canavan disease model mice (“CD mice”) reversed brain NAA elevation and improved motor function." (PMID 38282243, 2024). "Altered expression or function of SLC13A3 has also been associated with a reversible leukoencephalopathy, while its temporary ablation in a mouse model of Canavan disease was shown to reduce accumulation of N-acetylaspartate and to improve motor deficits." (PMID 35448538, 2022). "But that study did not illuminate the specific role of astroglial NaDC3, versus NaDC3 encoded by meningeal and renal Slc13a3,8 in mediating [NAAB] elevation and eliciting clinical neurological deficits in this murine Canavan disease model." (PMID 38282243, 2024). "To explore the specific pathophysiological significance of astroglial NaDC3 in Canavan disease, we examined the effects of astroglial Slc13a3 conditional knockout on [NAAB] and motor function in young adult CD mice." (PMID 38282243, 2024). "Are SLC13A3 and NaDC3 suitable targets for treating Canavan disease?" (PMID 38282243, 2024). "In addition SLC13A3 (NaDC3) has been suggested to participate in the pathogenesis of the two inborn metabolic diseases glutaric aciduria type 1 (GA1) and Canavan disease (CD)." (PMID 23506860, 2013).
Leukoencephalopathy (3 papers, 2021 to 2023). This term describes abnormality of the white matter of the cerebrum resulting from damage to the myelin sheaths of nerve cells. "It is the first study to link a-ketoglutarate accumulation and reversible leukoencephalopathy to biallelic variants of SLC13A3." (PMID 37794328, 2023). "(ii) Variants in the SLC13A3 gene, encoding the plasma membrane Na+/dicarboxylate cotransporter 3, have been associated with a reversible leukoencephalopathy during febrile illness." (PMID 33977262, 2021).
leukodystrophies (2 papers, 2023 to 2024). "More recently, whole body NaDC3 ablation achieved by constitutive Slc13a3 deletion was also found to prevent [NAAB] elevation and leukodystrophy in CD mice." (PMID 38282243, 2024).
prostate carcinoma (2 papers, 2018 to 2020). A carcinoma that arises from epithelial cells of the prostate gland. "Indeed, a plasma membrane Na(+)-dependent dicarboxylic acid transporter NaDC3 (also called SLC13A3), able to specifically upload succinate, has been reported in prostate cancer cells." (PMID 32266157, 2020).
depressive episodes (1 paper, 2024). "The most significant hits were for the number of manic episodes, with SLC13A3 as top gene in BP-I and TNRC6C in BP-II, followed by the number of depressive episodes, with MTSS1 as top gene in BP-I and DNAH14 in BP-II." (PMID 38865039, 2024).
Intellectual disability (1 paper, 2023). "Through state-of-the-art in silico studies, we explored the impact of these mutations, G448R in SLC9A6 and P493L in SLC13A3, on protein stability and function and their potential link to the development of intellectual disability." (PMID 37794328, 2023).
kidney stone (1 paper, 2022). "In contrast, PF-06761281 showed significant activity on the closely related transporters NaDC1 (gene symbol SLC13A2) and NaDC3 (gene symbol SLC13A3), leading to increased urinary calcium excretion, which may have unfavourable effects on bone health and kidney stone formation." (PMID 36005604, 2022).
liver cancer (1 paper, 2024). An epithelial or non-epithelial malignant neoplasm that arises from the liver. "For instance, SLC13A3 expression is elevated in human liver cancer samples." (PMID 39590609, 2024). "In mouse cells, β-catenin-activated liver cancer cells undergo autophagic ferroptosis and GSH depletion when SLC13A3 is silenced, which indicates that SLC13A3 may be a useful therapeutic target for the treatment of human liver tumors containing GOF CTNNB1 mutations." (PMID 39590609, 2024).
type 2 diabetes (1 paper, 2022). "A previous study has shown that the ELMO2 and SLC13A3 genes may also play a role in type 2 diabetes." (PMID 35964005, 2022).
viral infection (1 paper, 2024). "Constitutive Slc13a3 deletion in wild‐type mice has no obvious phenotypic effects other than increasing urinary NAA output, but, in humans, mutations that inactivate both alleles of SLC13A3 increase susceptibility to viral infection‐triggered acute reversible leukoencephalopathy." (PMID 38282243, 2024).
tumor (13 papers, 2014 to 2025). "Tumor cells take up itaconic acid from tumor-associated macrophages (TAMs) via SLC13A3, activating the NRF2-SLC7A11 pathway to evade ferroptosis mediated by the immune system and develop resistance to immune checkpoint blockade therapy." (PMID 41425581, 2025). "ITA can enter tumor cells and activate the nuclear factor erythroid-2 related factor 2 pathway in response to SLC13A3 transport, assisting tumor cells in resisting immunotherapy-induced ferroptosis." (PMID 41281760, 2025). "Recent studies have identified SLC13A3 as an importer of itaconate, with SLC13A3-mediated uptake contributing to tumor immune evasion, resistance to ferroptosis, and hepatic antibacterial innate immunity 48-50." (PMID 40521193, 2025). "SLC13A3 is a sarcosine transporter in tumor cells that confers resistance to ferroptosis and undermines the efficacy of tumor immunotherapy." (PMID 41425581, 2025). "Inhibition of SLC13A3 in syngeneic mouse tumor models synergizes with CTLA-4 blockade therapy to promote tumor-infiltrating T-cell immune responses, providing a potential novel therapeutic strategy for multiple cancer types." (PMID 41226585, 2025). "Inhibiting SLC13A3 can enhance T cell-mediated immune responses, break through the macrophage-mediated immunosuppressive barrier, and inhibit tumor growth and metastasis." (PMID 41425581, 2025). "Another potential target to block the inhibitory effects of itaconate on antitumor immunity is SLC13A3, which is identified as itaconate transporter for tumor cells." (PMID 40734168, 2025). "Under the rubric of tumor immunity, SLC13A3 activates the NRF2-SLC7A11 pathway by taking up itaconic acid, thereby conferring resistance to ferroptosis in tumor cells and reducing the efficacy of immune checkpoint blockade (ICB) therapy." (PMID 41425581, 2025). "Inhibiting the activity of SLC13A3, or pharmacologically interfering with its function, can increase the sensitivity of tumor cells to ferroptosis, curb tumor progression, and enhance the effectiveness of ICB." (PMID 41425581, 2025). "Within the tumor microenvironment, tumor cells take up itaconate via the itaconate transporter SLC13A3, thereby evading immune-mediated ferroptosis through activation of the Nrf2-SLC7A11 pathway." (PMID 41488637, 2025). "A recent study has shown that tumor cells uptake macrophage-derived itaconate through the SLC13A3, which contributes to tumor resistance to ferroptosis." (PMID 40482348, 2025). "Further analyses of tumor cell lines showed a positive correlation between R‐2‐HG uptake and the expression of sodium‐dependent SLC13A3." (PMID 38339779, 2024). "However, in tumour cells, succinate is taken up by sodium-coupled dicarboxylic acid transporters such as NaDC3 (SLC13A3) to fuel mitochondrial metabolism." (PMID 40722779, 2025). "SLC13A3 (a sodium-coupled citrate transporter) plays a key role in tumor immunity." (PMID 41425581, 2025). "Inhibiting SLC13A3 in tumor cells enhances the efficacy of immunotherapy." (PMID 40693608, 2025). "Additionally, SLC13A3-mediated itaconate uptake by tumor cells directly alkylates PD-L1 at cysteine 272 to promote PD-L1 stabilization leading to tumor immune evasion." (PMID 40734168, 2025). "It is also not surprising for the module to include the well-established proto-oncogene MYC which has a wide spectrum of downstream effectors, and the SLC family member SLC13A3, the expression of which found to be down-regulated in tumour cells over-expressing MYC family genes." (PMID 24523864, 2014). "It is important to note that SLC13A3 inhibitor, 2-(3-methylbenzyl) succinic acid, is able to overcomes ICB resistance and sensitizes xenograft melanoma tumor to ferroptosis in vivo." (PMID 40734168, 2025).
cancer (3 papers, 2018 to 2026). A tumor composed of atypical neoplastic, often pleomorphic cells that invade other tissues. "Concurrently, itaconate participates in regulating immune tolerance to cancer therapy via the transmembrane transporter SLC13A3." (PMID 41743716, 2026). "Membrane transport of succinate in viable cells is less well understood, although cancer cells have been shown to take up succinate in order to fuel mitochondrial metabolism via sodium-coupled dicarboxylic acid transporters such as NaDC3 (SLC13A3)." (PMID 33995417, 2021).
SLC13A3 also shares sentences with these, for which no sentence is quoted: acute myeloid leukemia (1 paper); Aicardi–Goutières syndrome (1); Alexander disease (1); amyotrophic lateral sclerosis (1); Barrett esophagus (1); Christianson syndrome (1); gastric cancer (1); glioma (1); leukemia (1); manic episodes (1); metabolic disease (1); neurodegenerative disease (1); ovarian carcinoma (1); Parkinson disease (1).